INS (insulin)
Diseases named in the same sentence as INS in open-access papers (continued):
Sharing a sentence is not in itself a finding about the gene and the disease.
diabetes (continued). "Type 1 diabetes mellitus is an autoimmune condition characterized by the destruction of pancreatic β-cells, necessitating insulin therapy to prevent life-threatening complications such as diabetic ketoacidosis." (PMID 39767759, 2024). "A total of 12.3% (3.6 million adults aged 20 years or older) of all U.S. adults with diagnosed diabetes started using insulin within a year of their diagnosis." (PMID 38672255, 2024). "T2DM is a systemic metabolic disorder marked by insulin resistance and inadequate insulin secretion, constituting 90% of all diabetes types." (PMID 39308824, 2024). "Bench-side dose accuracy results for an Ultra Low Cost Insulin Pump (ULCIP) were presented in the Journal of Diabetes Science Technology in December 2022, with an in depth presentation of the open-source hardware published in HardwareX." (PMID 39090697, 2024). "Transgenic VH125Tg.NOD mice, which harbor an increased percentage of insulin-specific B cells (1–2% of the total repertoire detectable by flow cytometry), show increased diabetes incidence compared to WT.NOD mice." (PMID 38651407, 2024). "Since GLP-1R is a target in diabetes mellitus, it enhances the proliferation of β-cells and insulin secretion in the pancreas and reduces plasma glucose levels." (PMID 38801466, 2024). "Metformin, a frequently prescribed medication for diabetes treatment, is known for its ability to curb liver glucose production, enhance insulin sensitivity, and boost muscle and liver glucose absorption." (PMID 38786121, 2024). "We found increased odds for medications for diabetes mellitus to both stage and grade, but decreased odds for insulin and oral hypoglycemic agents." (PMID 39157205, 2024). "Type 2 diabetes mellitus (T2DM) results from either reduced insulin production, insulin resistance, or both." (PMID 39349500, 2024). "It is therefore possible that SSRIs increase insulin secretion in people with diabetes who also have depression, leading to the documented improvements in glycaemia." (PMID 38888050, 2024). "Diabetes mellitus, the most prevalent metabolic disorder, is characterized elevated blood glucose levels due to insulin imbalances." (PMID 38716223, 2024). "The practice nurses were authorized to prescribe or adjust medications, order laboratory tests, and manage diabetes-related care except for initiating insulin therapy." (PMID 39765957, 2024). "Added GOx and insulin to the MOFs, where glucose triggered the degradation of the MOFs and subsequent release of insulin to manage diabetes or macular disease." (PMID 39639374, 2024). "There are different types of diabetes, but the most common ones are type 1 diabetes (insulin-dependent), type 2 diabetes (insulin-resistant), and gestational diabetes." (PMID 38673817, 2024). "In general, regular exercise has been proven to have numerous benefits for individuals with diabetes, including helping to control blood sugar, lipids, and weight, improving insulin sensitivity, and enhancing cardiovascular and pulmonary function." (PMID 39526249, 2024). "Through lifestyle modifications, insulin sensitivity can be significantly improved to effectively prevent or delay the development of diabetes and relevant complications." (PMID 38313368, 2024). "Insulin aspart is a recombinant rapid-acting human insulin analogue utilized in the treatment of type-1 and type-2 diabetes mellitus." (PMID 38378730, 2024). "For example, diabetes patients in this study included not only those with poor glycaemic control starting on insulin treatment but also those who had insulin intensification." (PMID 38530614, 2024). "Given selenium’s essential role in selenoprotein function and insulin signaling pathways, its management in diabetes is crucial." (PMID 39064810, 2024). "Diabetes mellitus is a collection of metabolic disorders marked by elevated levels of glucose in the blood due to irregularities in the generation or functioning of insulin." (PMID 38800782, 2024).
diabetes (continued). "GLP-1RAs are a group of medications originally developed for treating type 2 diabetes mellitus, which enhance insulin secretion in a glucose-dependent manner." (PMID 39459443, 2024). "Several lines of evidence indicate the role of CAV1 in insulin secretion and insulin signaling in diabetes and metabolic syndrome." (PMID 39464889, 2024). "Insufficient insulin synthesis, action, or both characterize the metabolic disorder known as diabetes." (PMID 38982468, 2024). "Although there is insufficient evidence that sacubitril/valsartan directly causes diabetes, angiotensin II is one of the key components of the RAAS, which promotes insulin secretion from pancreatic beta cells." (PMID 39193332, 2024). "Recent innovations, such as ultra-long-acting insulins and combination therapies like insulin icodec with semaglutide, offer the potential to reduce injection frequency and enable personalized diabetes care." (PMID 39734941, 2024). "The first and second sections provide information about diabetes and insulin, and the pros and cons of available treatment options." (PMID 39546450, 2024). "Therapeutic strategies that target SIRT1 activity have shown promise in increasing insulin sensitivity and glycemic control in diabetes." (PMID 38931292, 2024). "The reason can be attributed to social factors, low socioeconomic status, complexity of diabetes treatment, impact of insulin therapy on daily life, fear of injection, pain, or side effects that collectively influence patient adherence to therapy." (PMID 38610878, 2024). "Acutely, the insulin secretory properties of AA can improve glycaemic control in patients with diabetes, while its effect on glucagon secretion has the potency to impair glucose regulation and is associated with insulin resistance." (PMID 39114126, 2024). "Medicines for diabetes can include insulin injections, amylin mimetic drugs, alpha-glycosidase inhibitors, and other drugs to keep blood sugar levels in the normal range." (PMID 38686006, 2024). "STZ is a widely used antibiotic that selectively destroys pancreatic beta cells, leading to a reduction in insulin production and the development of diabetes in rodents." (PMID 39334700, 2024). "This review highlights the critical role of ongoing research and innovation in insulin therapy to meet the evolving needs of diabetes management." (PMID 39734941, 2024). "Type 1 diabetes mellitus (T1DM) is an autoimmune disorder that results in the destruction of insulin-producing pancreatic beta cells." (PMID 38783146, 2024). "Lipodystrophy is a common adverse effect of insulin subcutaneous injections, especially in patients with type 1 diabetes mellitus, with a prevalence estimated at 41.8% according to a recent meta-analysis." (PMID 39691127, 2024). "Diabetes is characterized by the presence of chronic hyperglycaemia resulting from insulin dysregulation, which also leads to inflammation or oxidative stress." (PMID 38190014, 2024). "For example, the correct diagnosis of MODY can prompt diabetes treatment cessation or the discontinuation of insulin depending on the MODY genes and clinical profile of the patients." (PMID 39420387, 2024). "Although fewer mothers were taking medication, over one-third of the mothers with diabetes were on dietary control, and roughly one-third were on insulin." (PMID 39840172, 2024). "Consumption of dietary fiber, especially soluble fiber, above the amount recommended by the American Diabetes Association (ADA) significantly improves glycemic management in people with T2DM, reduces high insulin levels, and helps to lower blood lipid levels." (PMID 39596859, 2024). "A whole chapter is devoted to the overlap of PD and diabetes aetiologies and reviews the contribution of insulin resistance to the initiation and progression of PD pathology." (PMID 38673943, 2024).
diabetes (continued). "Diabetes is a condition characterized by metabolic dysfunction, which includes reduced glucose tolerance, elevated fasting blood sugar levels, insufficient insulin production, or the presence of insulin resistance." (PMID 38921477, 2024). "In diabetes, chronic hyperglycemia results from an interruption of carbohydrate and fat metabolism owing to insufficient insulin secretion, insufficient insulin function, or both." (PMID 38464713, 2024). "In the context of diabetes, resistant dextrin and other prebiotics improve glucose metabolism and insulin sensitivity, highlighting prebiotics as a promising intervention for diabetes management and offering an alternative or adjunct to pharmacotherapy." (PMID 39200020, 2024). "Pax6 has been considered as a candidate gene for diabetes due to its role in transcriptional regulation of β-cell insulin secretion." (PMID 38356808, 2024). "The logistic regression equation included eight predictors(named ADOCHBIU): duration of diabetes, urinary microalbumin, oral hypoglycemic agents, mild cognitive impairment, insulin usage, hypertension, blood glucose monitoring, and abdominal circumference." (PMID 39610841, 2024). "AMPK signaling induction is an ideal strategy for reducing insulin resistance, improving glucose and lipid metabolism, and ameliorating diabetes complications." (PMID 38429982, 2024). "Among the 481 patients with insulin-dependent and insulin-independent diabetes mellitus in our study, 22 patients (4.57%) experienced a postoperative wound infection." (PMID 39063921, 2024). "Within patients with pre-diabetes, the insulin level is elevated to help maintain normal glucose levels." (PMID 39202546, 2024). "Age, gender distribution, diabetes duration, insulin delivery method, and insulin TDD were similar in normal weight, overweight, and obese patient groups (p = ns)." (PMID 39274516, 2024). "Of those with a diabetes diagnosis, 91.4% of women and 92.2% of men were on medication (insulin, tablets [e.g., Metformin or Amaryl], or both insulin and tablets)." (PMID 39033292, 2024). "The aim of these case series was to describe the use of smart insulin pens with connectivity for diabetes management in pregnancy." (PMID 39791645, 2024). "Exogenous hyperinsulinemia is the consequence of subcutaneous injection of synthetic insulin or its analogs in patients with diabetes mellitus." (PMID 38392069, 2024). "Diabetes, characterized by elevated blood glucose levels, manifests in various forms: Type 1 (insulin-dependent), Type 2 (insulin-resistant), and gestational diabetes occurring during pregnancy." (PMID 38671616, 2024). "The sequencing of insulin in the 1950s initiated the convergence of biotechnology and diabetes management, leading to the development of recombinant human insulin in 1982." (PMID 39766270, 2024). "This is particularly beneficial for patients with chronic conditions such as diabetes who require careful management of their insulin dosages, as fluctuations in blood sugar levels can lead to serious complications." (PMID 38720390, 2024). "Constituting a chronic metabolic disorder characterized by insufficient insulin production or the body’s ineffective use of insulin, diabetes ranks among the top 10 diseases contributing to mortality and morbidity." (PMID 38694982, 2024). "Patient A had premature onset of heart failure with reduced ejection fraction, DM nephropathy with reduced GFR of 50 ml/min, albuminuria, and severe diabetes mellitus on multiple insulin injections per day." (PMID 38321009, 2024). "Diabetes is a complex metabolic disorder characterized by elevated blood glucose levels due to defects in insulin secretion or the body’s response to insulin." (PMID 39766390, 2024). "It occurs most often in individuals with diabetes taking long-term insulin or in individuals with diabetes with degenerative complications." (PMID 39220553, 2024).
diabetes (continued). "Diabetes education is focused on dietary re-education, the application or use of insulin in its different routes of administration, in addition to measuring blood glucose and understanding other glycemic parameters." (PMID 38541647, 2024). "This approach is proposed as a crucial factor in ameliorating sarcopenia and obesity simultaneously in elderly with diabetes, improving insulin resistance, and ensuring the prevention of complications and overall health assurance." (PMID 38612998, 2024). "Type 2 diabetes mellitus (T2DM) is a persistent state of hyperglycemia and glucose intolerance caused by an inadequate response to insulin, followed by increased insulin production and subsequent insulin resistance." (PMID 39125322, 2024). "Diabetes mellitus (DM) is a chronic metabolic condition marked by elevated blood glucose levels resulting from impaired insulin secretion, insulin action, or both." (PMID 39091901, 2024). "Homeostatic model assessment and beta cell function (HOMA-beta) is used to estimate insulin secretion for the classification of diabetes and can have importance in clinical settings for optimizing diabetes treatment." (PMID 39013634, 2024). "Basal and bolus insulin requirements in children, adolescents, and young adults with type 1 diabetes mellitus on continuous subcutaneous insulin infusion (csii): effects of age and puberty." (PMID 39196351, 2024). "Vitamin D is a pleiotropic hormone that regulates numerous biological functions, such as blood pressure, immunological responses and insulin production, and exerts beneficial effects in preventing cardiovascular diseases, diabetes, and certain types of cancer." (PMID 38892509, 2024). "Insulin resistance and β-cell dysfunction are the two main insulin-related disorders that define this kind of diabetes." (PMID 38813307, 2024). "The novel idea of light-activated insulin is revolutionary for controlling blood glucose levels, providing a fresh approach to treating diabetes." (PMID 38542928, 2024). "Type 1 diabetes mellitus is an autoimmune disorder characterized by infiltration of the islets of Langerhans by immune cells and by selective elimination of the insulin-secreting β cells." (PMID 38720885, 2024). "This evidence supports the potential of pig islets to survive and function in humans, offering a promising avenue for diabetes treatment by reducing insulin dependency." (PMID 38464515, 2024). "Following the interventions, 46.3% of the patients after IST showed a worsening of the diabetes mellitus level either by new dependency on insulin or new manifestation." (PMID 38347181, 2024). "The beneficial impacts of omega-3 fatty acids on prediabetes and diabetes metabolism can be attributed to their antioxidant, anti-inflammatory, antilipidemic, antiadipogenesis, insulin sensitivity-enhancing, and insulin resistance-improving properties." (PMID 39031306, 2024). "This sense of being defeated by diabetes was also shared by Saara (T1D), who grew frustrated with the variability of her daily blood glucose and when her usual insulin correction and hydration strategies to address a high glucose did not work." (PMID 38570742, 2024). "Approximately 64% had disease duration for more than 10 years, 72.5% followed a diet for diabetes, 90.4% reported taking anti-diabetic oral medications, 9.6% reported using insulin, and 14.8% reported using both oral medications and insulin." (PMID 39058533, 2024). "Nearly half (47.5%) had diabetes for 10 years or more, 65.5% were managed with oral hypoglycemic drugs and (16.0%) were managed with both oral hypoglycemic drugs and insulin." (PMID 39415165, 2024). "Together, the protective genes at Idd5 and Idd3 provide almost complete protection from diabetes, insulitis, and the formation of insulin autoantibodies." (PMID 39796447, 2024). "Type I diabetes mellitus stands as an autoimmune variety of diabetes that commonly emerges in young individuals as a consequence of an insufficient supply of insulin." (PMID 39771551, 2024).
diabetes (continued). "Labeling foods with carbohydrates and consuming a fixed amount of carbohydrates in fixed meals is more common in people with diabetes mellitus who use a basal-bolus insulin regimen." (PMID 39767064, 2024). "Out of the 15 participants who knew they had diabetes 11(73%) were taking oral hypoglycaemic agents and 8/15 (53.3%) were taking insulin." (PMID 38768141, 2024). "Timely evaluation of the insulin secretion function of islets in children with obesity is essential for early intervention to prevent diabetes." (PMID 40302954, 2024). "Another relevant attraction of this contribution is that the results demonstrated the independent involvement of adiposity, lipid metabolism, insulin synthesis, and inflammation measurements and markers that modulated glycemia levels before diabetes emergence." (PMID 39767255, 2024). "As the Japanese KCNK16 MODY family showed a greater insulin requirement compared to the patients from Australian KCNK16 MODY family, diversity in diabetes phenotypes likely occurs with KCNK16 mutations." (PMID 38700926, 2024). "A 12-week aerobic exercise training increases the expression of adipokine omentin in visceral AT, leading to the regulation of insulin sensitivity, glucose homeostasis, and anti-inflammatory effects against type 2 diabetes mellitus." (PMID 38786764, 2024). "Its polyphenolic compounds support the prevention and management of metabolic diseases, such as diabetes and hyperlipidemia, by improving insulin sensitivity, lowering blood glucose levels, and regulating lipid metabolism." (PMID 39771257, 2024). "Its likely association with type 2 diabetes mellitus is the regulatory role of serine in the actions of N-methyl-D-aspartate (NMDA) receptors, which inhibit insulin secretion by pancreatic beta cells." (PMID 39561140, 2024). "Metabolomics research has linked bile acids, branched-chain amino acids (BCAAs), and by-products of intracellular fatty acid oxidation to diabetes, glycemic control, and insulin resistance." (PMID 38169662, 2024). "In diabetes management, these materials offer innovative solutions for insulin delivery, β-cell protection, and improvement of insulin resistance, as well as support for islet transplantation, marking significant strides in addressing this chronic condition." (PMID 39684868, 2024). "Her maternal grandfather, diagnosed with diabetes at age 40, was treated with insulin and medication." (PMID 39221226, 2024). "Clinical parameters and serum levels of HGF, EGF, insulin, and nitrogen-related compounds in control subjects and patients with Type 2 Diabetes Mellitus, with results expressed as medians." (PMID 38654922, 2024). "Diabetes mellitus (DM) is a metabolic disease characterized by hyperglycemia resulting from insufficient control of blood glucose levels and impaired insulin secretion." (PMID 39839113, 2024). "Diabetes mellitus (DM) involves hyperglycaemia due to insulin inactivity or insufficiency and is increasingly becoming a global health issue due to its high morbidity and mortality." (PMID 38406276, 2024). "Type 2 diabetes, which accounts for over 90% of all diabetes cases globally, is a metabolic condition marked by insufficient insulin production and resistance, leading to high blood sugar levels." (PMID 38469145, 2024). "Such carbohydrate overestimation poses considerable risks (e.g., poor glycaemic control and hypoglycaemic episodes) for patients with diabetes who rely on carbohydrate counting to calculate fixed-dose insulin." (PMID 39125452, 2024). "During this trip, they heard daily reports of people with diabetes being treated with insulin, and Marie Krogh, who had type 2 diabetes, took a special interest in the treatment." (PMID 38540146, 2024). "Diabetes technologies such as continuous subcutaneous insulin infusion (CSII) and continuous glucose monitoring (CGM) can reduce overall episodes of hypoglycaemia, improve glycaemic control and decrease the risk of microvascular complications." (PMID 38875308, 2024).